DDR1 (discoidin domain receptor tyrosine kinase 1)
Diseases named in the same sentence as DDR1 in open-access papers (continued):
Sharing a sentence is not in itself a finding about the gene and the disease.
colon carcinoma (continued). "DDR1 was expressed on both cell membranes and cytoplasm in colon cancer." (PMID 31116512, 2019). "Indeed, invasion and metastatic processes were decreased by DDR1-BCR signaling axis inhibition in vivo in colon carcinoma suggesting that DDR1 could be an effective therapeutic target in this cancer." (PMID 35205677, 2022). "However, frequent high expression of DDR1 in colon cancer could be further explored as a potential therapeutic target in this indication." (PMID 35205677, 2022). "Our results demonstrated in univariate analysis that the clinico-pathological and molecular characteristics associated with DDR1 expression in colon adenocarcinoma were: male sex, left colon tumor localization, BRAF wild-type status, and absence of the expression of the serrated marker Annexin A10." (PMID 35205677, 2022). "Since DDR1 phosphorylation could be responsible of growth inhibition, we evaluated the impact of nilotinib (50 nM), a receptor tyrosine kinase inhibitor with high potency against DDR1, on colon carcinoma cell proliferation using both control and HT-29DDR1–GFP cells." (PMID 32582700, 2020). "In summary, anti‐DDR1 ADC was highly efficacious in DDR1‐expressing colon cancer xenograft models and exhibited acceptable safety profiles in preliminary animal studies, suggesting that anti‐DDR1 ADC may be a promising therapeutic for the treatment of patients with colon cancer." (PMID 31116512, 2019). "Our data showed that DDR1‐based ADC could be a promising therapeutic agent for colon cancer." (PMID 31116512, 2019). "In our study, DDR1‐positive human colon cancer xenografts resistant to oxaliplatin were eliminated by T4H11‐DM4 in vivo, which indicated that the combination therapy of T4H11‐DM4 and other small molecular inhibitor might be good option to overcome chemotherapy‐resistance." (PMID 31116512, 2019). "In colon cancer, DDR1 interacts with LRP1, a lipoprotein receptor inducing DDR1 endocytosis, thereby controlling its expression at the plasma membrane." (PMID 33917302, 2021). "In this study, we show DDR1, an RTK, is a promising candidate target for ADC therapy for colon carcinoma." (PMID 31116512, 2019). "We selected colon cancer cell lines HT‐29, HCT116 and HCT15 expressing different levels of DDR1 to establish mouse subcutaneous tumor models." (PMID 31116512, 2019). "Furthermore, the receptor tyrosine kinases discoidin domain receptors DDR1 and DDR2 are also involved in type 1 collagen-mediated invasion and metastasis of colon carcinoma." (PMID 36741692, 2022). "Similar study on cell proliferation have been conducted using RKO colon carcinoma cells that do not express DDR1." (PMID 32582700, 2020). "Overall, our findings highlight the potential of DDR1‐targeted ADC and may facilitate the development of a new effective therapeutic strategy for colon cancer." (PMID 31116512, 2019).
non-small cell lung carcinoma (19 papers, 2007 to 2026). A group of at least three distinct histological types of lung cancer, including non-small cell squamous cell carcinoma, adenocarcinoma, and large cell carcinoma. "DDR1, a tyrosine kinase receptor, has emerged as a potential new therapeutic target for non-small cell lung cancer given its association with poor prognosis among affected patients." (PMID 38136314, 2023). "Two studies reported that increased DDR1 expression was associated with poor survival of patients with non-small cell lung cancer." (PMID 28143619, 2017). "Discoidin domain receptor tyrosine kinase 1 (DDR1), a collagen receptor associated with poor prognosis in non-small cell lung cancer, was the most highly expressed transmembrane receptor." (PMID 22375630, 2012). "DDR1 inhibition promotes ferroptosis and restores gefitinib sensitivity in non-small cell lung cancer (NSCLC)." (PMID 41492134, 2026). "DDR1 is highly phosphorylated in non-small cell lung cancer (NSCLC), and DDR1 overexpression is associated with poor prognosis in NSCLC." (PMID 25992553, 2015). "DDR1 protein levels were elevated in 100% of patients with primary and metastatic brain tumors, in 61% of patients with non-small cell lung cancer, and in 64% of patients with invasive lung adenocarcinoma." (PMID 21541037, 2011). "Additionally, type I collagen (Col I) not only upregulates DDR1 expression but also activates DDR1, promoting the migration and invasion of non-small cell lung cancer (NSCLC) cells." (PMID 40713963, 2025). "Furthermore, we found other pleiotropic genes as drug targets for lung and GIT diseases, such as pralsetinib targeting DDR1 for the treatment of non-small cell lung cancer and trimebutine targeting CACNA1D for the treatment of IBS." (PMID 38102678, 2023). "DDR1 was found to be a prognostic marker for non-small-cell lung carcinoma (NSCLC) patients." (PMID 34207360, 2021). "Tumour samples from 146 non-small cell lung carcinoma (NSCLC) patients were analysed for relative expression of DDR1 and DDR2 using quantitative real-time PCR (qRT-PCR)." (PMID 17299390, 2007).
glioma (18 papers, 2012 to 2025). A benign or malignant brain and spinal cord tumor that arises from glial cells (astrocytes, oligodendrocytes, ependymal cells). "qRT-PCR data showed that CRISPRa-induction of DDR1 significantly upregulated DDR1 transcripts in control glioma cells and glioma cells that were transduced with LINC02454 LNAs." (PMID 38177123, 2024). "By contrast, we also show that LINC02454 can reduce glioma cell TMZ sensitivity by promoting expression of DDR1 (Discoidin domain receptor 1)." (PMID 38177123, 2024). "Our lead molecule DDR1‐IN‐1, selected through our in vitro model for its potential therapeutic effects against glioma invasiveness, has been confirmed to cross the BBB, enhancing its applicability in brain tumor treatments." (PMID 38384234, 2024). "DDR1 upregulation also significantly decreased caspase 3/7 activities in glioma cells treated 48 h with TMZ (1 mM)." (PMID 38177123, 2024). "By contrast, LINC02454 activity also decreased glioma cell TMZ sensitivity by promoting DDR1 expression." (PMID 38177123, 2024). "Comparing the expression of DDR1 gene in various tumor models revealed DDR1 to be elevated in all tumors with maximal expression in brain cancers, low-grade gliomas (LGG), and GBM [source: GEPIA; datasets, TCGA (tumor), GTEx (Normal)]." (PMID 35664781, 2022). "Genetic inhibition of DDR1 in human colon, glioma and pancreatic adenocarcinoma carcinoma cells shows impaired growth of tumor xenograft in mice." (PMID 31116512, 2019). "Regulation of cell migration by DDR1 was reported in various cancer cell lines including glioma, hepatocarcinoma, lung, pancreas, colorectal, and breast carcinoma." (PMID 27014069, 2016). "Targeting DDR1 with siRNA in glioma and pancreatic adenocarcinoma cell lines inhibited tumor cell proliferation in vitro and impaired subcutaneous xenograft tumor growth in mice." (PMID 27014069, 2016). "We found that LINC02454 KD downregulated DDR1 transcription and increased glioma cell TMZ sensitivity, consistent with a previous study of GBM showing that inhibition of DDR1 combined with radiochemotherapy including TMZ increased TMZ sensitivity and prolonged patient survival." (PMID 38177123, 2024). "On the other, LINC02454 promoted DDR1 expression to decrease glioma cell sensitivity to TMZ." (PMID 38177123, 2024). "Our findings also indicate that SORBS2 and DDR1 could be therapeutic targets to enhance glioma cell TMZ sensitivity." (PMID 38177123, 2024). "DDR1 upregulation decreased LDH release from glioma cells treated 48 h with TMZ (1 mM)." (PMID 38177123, 2024). "In conclusion, our study shows that LINC02454 increases glioma cell TMZ sensitivity by maintaining chromatin interactions between the SORBS2 gene and a LINC02454 enhancer and at the same time can decrease TMZ sensitivity of glioma cells by promoting DDR1 expression." (PMID 38177123, 2024). "To confirm this function, we used the CRISPRa system to activate DDR1 in U251 glioma cells." (PMID 38177123, 2024). "In preliminary studies DDR1‐IN‐1 has shown survival benefits in a mouse glioma model." (PMID 38384234, 2024). "DDR1 expression profiles were shown in single cells of glioma, MEL, and RCC by a t-SNE diagram." (PMID 37031216, 2023). "Previous studies have demonstrated that discoidin domain receptor tyrosine kinase 1 (DDR1) could sensitize glioma cells to therapies through its efficient induction of autophagic cell death." (PMID 33663509, 2021). "Glioma cells with high DDR1 displayed enhanced migration and invasion, which could be reversed by an anti-DDR1 antibody." (PMID 25369402, 2014). "DDR1 was also shown to enhance cell adhesion to collagen I in glioma and pituitary adenoma cells." (PMID 23284937, 2012). "Similarly, EMT and stemness programs are positively associated with DDR1 in renal cell carcinoma (RCC), RB, and glioma, supporting the hypothesis that DDR1-mediated collagen signaling fosters cellular plasticity and therapy resistance." (PMID 40869052, 2025).
glioma (continued). "Thus, LINC02454 may regulate DDR1 and alter glioma cell TMZ sensitivity through the MAPK pathway, although further studies are required for confirmation." (PMID 38177123, 2024). "Besides, monoclonal antibody 48B3 specific to DDR1 could decrease glioma cell invasion and adhesion." (PMID 31116512, 2019). "Several eRNAs, including TMZR1-eRNA and LINC02454, influence sensitivity to temozolomide (the main chemotherapeutic agent for glioma) by modulating STAT3 and DDR1 signaling." (PMID 41154382, 2025). "DDR1 functions physiologically by activating MAPK, PI3K/Akt and other signaling pathways, many of which reportedly regulate TMZ resistance of glioma cells." (PMID 38177123, 2024). "An important finding reported here is that SORBS2 and DDR1 are two major genes regulated by LINC02454, and that both regulate glioma cell sensitivity to TMZ." (PMID 38177123, 2024). "ChIRP-qPCR results also showed significant enrichment of LINC02454 at the DDR1 locus in control but not LINC02454 KD glioma cells, suggesting that LINC02454 binds to that locus and regulates DDR1 transcription." (PMID 38177123, 2024). "DDR1 is highly expressed in pediatric high-grade gliomas as well as adult gliomas, irrespective of grades, where cells overexpressing the receptor show enhanced invasion and migration, likely as a result of activation of MMP2." (PMID 33673213, 2021). "For example, DDR1 overexpression promoted cell adhesion to collagen in several cell types such as leukocytes, glioma cells and pituitary adenoma cells, while the absence of DDR1 reduced adhesion to collagen in smooth muscle cells and mesangial cells." (PMID 23284937, 2012).
gastric cancer (17 papers, 2017 to 2025). A primary or metastatic malignant neoplasm involving the stomach. "High DDR1 expression was significantly associated with poor overall survival (OS) in patients with breast, lung, and gastric cancers." (PMID 40869052, 2025). "Generally, DDR1 level is significantly and negatively associated with immune infiltration in STAD, revealing that DDR1 plays a specific role in gastric cancer through immune cell infiltration, especially CD8+ T cells, macrophages, and DCs." (PMID 35935941, 2022). "DDR1 expression is also increased in the stroma of invasive breast tumors and in gastric cancer-associated fibroblasts that enhance peritoneal tumorigenesis." (PMID 32664526, 2020). "In particular, DDR1 expression was associated with poor survival in patients receiving adjuvant chemotherapy after resection for gastric cancers." (PMID 28143619, 2017). "First, we analyzed DDR1 mutations in gastric cancer using the cBioPortal database." (PMID 35935941, 2022). "Overall, DDR1 was implicated in invasion, metastasis, and immune infiltration of gastric cancer." (PMID 35935941, 2022). "Gastric cancer cells express DDR1/2, and DDR1/2 are associated with the development of GC, based on a search of the GeneCards database, Oncomine and some studies." (PMID 30154451, 2018). "Suppressed HIF‐1α ubiquitination and degradation by DDR1 was reported to be involved in the malignant progression of gastric cancer." (PMID 40515512, 2025). "In gastric cancer, DDR1 knockdown significantly reduces angiogenesis and lymphangiogenesis, as well as lymph node and liver metastasis, highlighting its critical role in metastasis." (PMID 40563472, 2025). "In our previous work, DDR1 was markedly overexpressed in colorectal and gastric cancers, where it predicted poor survival and low immune cell infiltration, underscoring its multifaceted contribution to tumor biology." (PMID 40869052, 2025). "The results showed that DDR1 expression significantly affected the infiltration of various TIICs in gastric cancer, especially CD8+ cells, macrophages, and DCs." (PMID 35935941, 2022). "To comprehensively understand the molecular mechanism of DDR1, we explored genes and proteins interacting with DDR1 in gastric cancer using databases." (PMID 35935941, 2022). "Drugs targeting DDR1-ECD will help to reduce immune exclusion in gastric cancer, enhance T-cell infiltration, and reduce NETs, thereby improving the tumor immune microenvironment and slowing tumor progression." (PMID 35935941, 2022). "We found that DDR1 expression levels were highly upregulated in many cancers, and highly expressed DDR1 significantly affected the prognosis of gastric cancer." (PMID 35935941, 2022). "On the basis of previous screening studies, our study selected DDR1 as a target to investigate its role in gastric cancer." (PMID 35935941, 2022). "Taken together, these results suggest that the high expression of DDR1 affects the prognosis of different gastric cancer classifications to varying degrees." (PMID 35935941, 2022). "Here, we primarily evaluated DDR1 expression in gastric cancer and its cell lines using multiple databases." (PMID 35935941, 2022). "Specially, targeting DDR1 is suggested to have a good therapeutic potential for metastatic advanced gastric cancer." (PMID 35935941, 2022). "Following the assessment of overall infiltration in gastric cancer, we further explored the correlation between DDR1 and various immune cell markers." (PMID 35935941, 2022). "Based on samples from TCGA-STAD in the UALCAN database, DDR1 expression levels in the context of various clinical parameters of gastric cancer were examined." (PMID 35935941, 2022). "Overall, our study demonstrates the multiple potentials of DDR1 in the immunotherapy of gastric cancer, including immune infiltration and tumor invasion, and also expands the direction of DDR1 signaling mechanism research." (PMID 35935941, 2022).
gastric cancer (continued). "In summary, this study deepens our understanding of the various roles of DDR1 in the progression of gastric cancer and also demonstrates the potential clinical value of DDR1 as a therapeutic target for gastric cancer." (PMID 35935941, 2022). "After analysis, we discovered that DDR1 was highly expressed and significantly connected with poor prognosis in gastric cancer." (PMID 35935941, 2022). "Correlation between DDR1 expression and different clinicopathological characteristics in gastric cancer via Kaplan–Meier plotter." (PMID 35935941, 2022). "In gastric cancer cells, depletion of DDR1 suppresses the expression of key angiogenic factors such as VEGF-A, VEGF-C, and PDGF-B (Platelet-Derived Growth Factor B) and leads to necrosis in vivo, as a consequence of impaired angiogenesis." (PMID 33917302, 2021). "DDR1, in renal cell carcinoma and in gastric cancer cells, induces the secretion of angiogenic factors involved in endothelial cell tube formation in vitro." (PMID 33917302, 2021). "In gastric cancer, a correlation among DDR1, E-cadherin, and vimentin has been demonstrated in cancer tissues." (PMID 33917302, 2021). "In vivo, on gastric carcinoma, pharmacological inhibition of DDR1 in the mouse xenograft model impeded CAF-induced tumorigenesis with a reduction in the number of tumor nodules." (PMID 33917302, 2021). "In gastric carcinoma, CAFs induced the upregulation of DDR1 in tumor cells in vitro by potently activating STAT3, increasing its tumorigenic potential." (PMID 33917302, 2021). "Our results showed that 50.5% of gastric cancer tissues are positive for DDR1 expression, and positive DDR1 expression was significantly correlated with a poor prognosis (P = 0.015)." (PMID 28143619, 2017). "DDR1 staining was generally observed at the cell membrane or in the cytoplasm of tumor cells, and 50.5% of gastric cancer tissues showed positive DDR1 expression." (PMID 28143619, 2017). "We observed that a DDR1 inhibitor, 7rh benzamide, suppressed tumor growth in gastric cancer xenografts." (PMID 28143619, 2017). "We examined the effect of collagen-induced activation of DDR1 on cell signaling, tumorigenesis, and cell migration in gastric cancer cell lines, and tumor growth in a xenograft animal model of gastric cancer." (PMID 28143619, 2017). "To extend these findings, we investigated the expression of DDR1 in various human gastric cancer cell lines." (PMID 28143619, 2017). "In the current study, we demonstrated for the first time the correlation between DDR1 expression and worse overall prognosis in gastric cancer patients." (PMID 28143619, 2017). "Here, we investigated the clinical correlation of DDR1 expression in gastric cancers and determine if a novel DDR1-targeting agent, 7rh benzamide, can suppress cancer progression." (PMID 28143619, 2017). "We also demonstrated that collagen was able to activate DDR1 and increase the clonogenicity and migration of gastric cancer cells." (PMID 28143619, 2017). "We therefore suggest the use of specific DDR1 inhibitors as therapeutic agents to suppress gastric cancer progression." (PMID 28143619, 2017). "Taken together, these findings supported the notion that the expression of DDR1, which uses extracellular collagen as a ligand, is a good candidate biomarker to predict gastric cancer prognosis." (PMID 28143619, 2017). "Here, we assessed the role of DDR1 in mediating the aggressive phenotype of gastric carcinoma and its potential as a therapeutic target." (PMID 28143619, 2017). "We conducted DDR1 immunohistochemistry using a tissue microarray of 202 gastric carcinoma specimens." (PMID 28143619, 2017). "Our findings suggest a key role for DDR1 signaling in mediating the aggressive phenotype of gastric carcinoma." (PMID 28143619, 2017). "Other studies also reported that DDR1 could increase invasion and metastatic spread of gastric cancer via EMT." (PMID 35935941, 2022).